TNF (tumor necrosis factor)
Diseases named in the same sentence as TNF in open-access papers (continued):
Sharing a sentence is not in itself a finding about the gene and the disease.
Myocardial fibrosis (continued). "The findings indicate a potential involvement of B cells that secrete TNF-α in the development of myocardial fibrosis." (PMID 39917605, 2024). "Proinflammatory cytokines such as TNF-α and IL-6 stimulate cardiac oxidative stress and coronary artery dysfunction, leading to cardiac remodeling, myocardial fibrosis, and diastolic dysfunction." (PMID 39365793, 2024). "In rats, cardiac function, serum levels of cardiac enzymes, apoptosis, myocardial fibrosis, and levels of IL-1β, IL-18, TNF-α, TLR2, and pyroptosis-related molecules were detected." (PMID 39018487, 2024). "Reportedly, increased copper levels can stimulate increases in the serum levels of tumor necrosis factor α (TNF-α) and C-reactive protein in rats, contributing to inflammatory damage in multiple organs, including the heart, and inducing myocardial fibrosis." (PMID 39850564, 2024). "Cell releases IL-6 and TNF- α can induce the decline of myocardial cell vitality and apoptosis, accelerate the secretion of a large amount of collagen and myocardial fibrosis in myocardial tissue, damage myocardial function." (PMID 37986153, 2023). "It has been reported that hUMSCs injections dampened rat myocardial fibrosis and dysfunction via inhibiting inflammatory factor TNF-α." (PMID 35849219, 2022). "Masson staining also showed that TNF-Tg mice had obvious myocardial fibrosis compared with the control group." (PMID 35600883, 2022). "Cytokines, including proinflammatory signaling IL-1β, IL-6, TNF-α, and myocardial fibrosis signaling TGF-β, were significantly reduced in the BZ." (PMID 35571187, 2022). "In our study, we demonstrated relationships between tEAT and levels of pro-inflammatory cytokines (TNF-α and IL-6), adipokines (leptin and adiponectin), and markers of myocardial fibrosis (MMP-3, TGF-β, and collagen)." (PMID 34088886, 2021). "TNF-α incites cardiac fibroblast apoptosis and provokes adverse cardiac remodeling; moreover, TNF-α triggers cardiac fibroblast adhesion and aggravates myocardial fibrosis." (PMID 32382291, 2020). "The inhibition of p38 MAPK attenuates TNFα secretion and reverses myocardial fibrosis leading to improved cardiac function." (PMID 31689891, 2019). "AF patients indicated a higher concentration of TNF-α and IL-6, lymphomonocyte infiltration, as well as the degree of myocardial fibrosis." (PMID 30386232, 2018). "Based on the previous studies and the present study, we suggest that the effect of ivabradine on myocardial fibrosis is related to the reduction of the proinflammatory cytokines TNF-α, IL-1β, and IL-6." (PMID 27847478, 2016). "NF-κB contributes to myocardial fibrosis pathogenesis because it regulates genes/proteins important for disease progression, including cytokines (e.g., TNF-α), interleukins (e.g.,IL-1β)." (PMID 26846090, 2016). "TNF-α induces myocardial fibrosis by inhibiting collagen phagocytosis in the heart and up-regulating AT1R on cardiac fibroblasts, leading to enhancement of the effects of Ang II." (PMID 26378790, 2015). "Transgenic mice with cardiac restricted overexpression of TNF-α develop progressive myocardial fibrosis, possibly due to TNF-α mediated signaling of AT1R." (PMID 26378790, 2015). "SB203580 suppressed myocardial fibrosis and LV remodelling, attenuated p38 activation and expression of TNF-α, α-SMA and collagen I." (PMID 25204838, 2015). "Myocardial fibrosis was markedly increased in transgenic mice with cardiac-specific overexpression of TNF-α." (PMID 25768281, 2015). "Inflammatory cytokines, including TGF-β1, TNF-α and IL-1β, play crucial roles in myocardial fibrosis and the pathological progression of left ventricular remodeling following MI." (PMID 24807380, 2014). "Activated NF-κB increases the expression of TGF-β1, TNF-α and IL-1β, which subsequently activates collagen deposition and myocardial fibrosis that lead to myocardial remodeling and HF." (PMID 24807380, 2014).
Myocardial fibrosis (continued). "The pro-inflammatory cytokines, including TGF-β1, TNF-α, and IL-1β, play crucial roles in myocardial fibrosis and the pathological progression of LV remodeling by inducing inflammatory action via the NF-κB pathway." (PMID 24260217, 2013). "Studies in vitro showed that cardiac-restricted overexpression of TNF-α induces myocardial fibrosis and diastolic dysfunction." (PMID 23446214, 2013). "Elevated levels of MMP2, MMP9 and TNFα in these mice were linked to increased production of collagen types I and III by CFBs in a TGFβ-dependent manner, leading to myocardial fibrosis." (PMID 22943504, 2012). "Transgenic mice with targeted overexpression of TNFα develop progressive myocardial fibrosis, diastolic dysfunction, and adverse cardiac remodeling." (PMID 23079082, 2012). "The anti-inflammatory properties of the Mediterranean diet, driven by its high content of omega-3 fatty acids, polyphenols, and monounsaturated fats, reduce the pro-inflammatory cytokine profile of EAT, including TNF-α and IL-6, which are known to promote myocardial fibrosis and dysfunction." (PMID 39860003, 2025). "TNF-α induces myocardial fibrosis through multiple pathways." (PMID 40881586, 2025). "Besides amplifying the inflammation and stimulating myocardial fibrosis, TNF-α can directly inhibit myocardial contraction by reducing sarcoplasmic reticulum proteins and impairing the efficiency of calcium uptake and release in cardiomyocytes." (PMID 41479659, 2025). "Notably, DCM patients exhibit an increased presence of TNF-α-secreting B cells, suggesting their involvement in myocardial fibrosis." (PMID 37512058, 2023). "In a rat model of DCM, inhibiting TNF-α could reduce myocardial fibrosis and improve cardiac function." (PMID 37479697, 2023). "The inflammatory cascade reaction mediated by neutrophil granulocyte and mononuclear macrophages is one of the common mechanisms leading to the myocardial fibrosis, which can secrete a variety of proinflammatory cytokines such as TNF-α, IL-1β, and IL-6, leading to the myocardial fibrosis." (PMID 36105253, 2022). "Thus, TNF-α, a widely study cytokine, plays a key role in the pathogenesis and progression of left ventricular remodeling, and its excessive amount leads to myocardial fibrosis and cardiomyocyte apoptosis." (PMID 34088886, 2021). "TNFα induces myocardial fibrosis by inhibiting phagocytosis of collagen in the heart." (PMID 32722688, 2020). "WD-sedentary mice had significantly higher protein levels of TNF-α (a key pro-inflammatory cytokine that contributes to myocardial fibrosis) and lower protein levels of IL-10 (an anti-inflammatory cytokine that is involved in the protection against WD-induced inflammation) than ND-sedentary mice." (PMID 29218015, 2017). "For TNF-alpha, a contribution to myocardial fibrosis in DCM has been suggested in the literature." (PMID 27822484, 2016). "However, there is clear evidence that TNFSF members such as TNFα or FasL are also directly involved in myocardial fibrosis." (PMID 24611063, 2014). "Finally, both TNFα and FasL overexpression is associated with increased levels of TGF-β1, an important inducer of myocardial fibrosis." (PMID 24611063, 2014). "NF-κB contributes to myocardial fibrosis pathogenesis because it regulates genes/proteins important for disease progression, including cytokines (e.g., TNF-α), interleukins (e.g., IL-6), growth factors (e.g., TGF-β), and adhesion molecules (e.g., intercellular adhesion molecule)." (PMID 24171042, 2013). "From molecular analyses, we concluded that the reverse process of myocardial fibrosis was dependent on upregulation of PPARα and PPARγ expression, downregulation of NF-κB expression, and suppressing TNF-α, ICAM-1, and MCP-1 production through the NF-κB signaling pathway." (PMID 24171042, 2013). "CD4+ Th2-type immune responses, mediated by IL-4, are believed to drive fibrotic process and recent study revealed that TNF-α-Secreting B Cells may contribute to myocardial fibrosis in DCM." (PMID 24023968, 2013).
Myocardial fibrosis (continued). "In addition, compared with the Model group, ASS significantly alleviated myocardial injury, reduced the release of inflammatory cytokines TNF-α and IL-β, improved the oxidative stress state, reduced the release of NT-propBNP, Ang II, ET-1 and inhibited myocardial fibrosis." (PMID 41828600, 2026). "In the male Wistar rats treated with 1 mg/kg of LPS for three weeks, thymoquinone at 2, 5, and 10 mg/kg doses also could improve myocardial fibrosis through decreasing the cardiac level of IL‐1β, TNF‐α, NO, and MDA, and enhancing the total thiol content and SOD and CAT activity." (PMID 39898124, 2025). "T2DM might be associated with DCM, which is characterized by myocardial fibrosis and which might be due to enhanced oxidative stress, upregulation of inflammatory cytokines (TGF-β, TNF-α) and apoptotic proteins (caspase-3) and increased activity of myocardial sympathetic nerve fibers." (PMID 32106580, 2020). "Th17 cells may promote myocardial fibrosis through serial effectors, such as IL-6 and TNF-α." (PMID 23977238, 2013). "Left atrial myocardial fibrosis was positively correlated with the level of proinflammatory and profibrotic cytokines/chemokines, IL‐6, MCP‐1, and TNF‐α, in EAT and myocardial fibrosis is a known substrate for atrial fibrillation." (PMID 39167271, 2025). "In summary, CDDP regulates inflammatory response mainly by affecting factors such as TNF-α, NF-κB, IL-6, JNK, KDM4A, and FOXO1, thus inhibiting myocardial fibrosis and improving cardiac function." (PMID 40881586, 2025). "Monocyte activation, IL-6, TNF-α production, and NLRP3 inflammasome activation are heightened in CRS, contributing to vascular and myocardial fibrosis." (PMID 40806569, 2025). "Our study conjointly demonstrates that ZL can down-regulate the expression of p-P38MAPK, TNF-α, α-SMA, and Collagen-I, thereby relieving myocardial fibrosis in mice with DCM, consistent with the findings of earlier studies." (PMID 40373162, 2025). "In addition, IL-16 enhances the secretion of inflammatory cytokines such as IFN-γ, IL-10, IL-16, TNF-α, and IL-15 by monocytes and mature macrophages, which promotes the development of myocardial inflammation and thus plays an indirect role in promoting the development of myocardial fibrosis." (PMID 40881586, 2025). "Patients with LVDD exhibited the highest levels of TNF-α and CRP, aligning with prior findings that link systemic inflammation to myocardial fibrosis and diastolic dysfunction." (PMID 39727643, 2024). "A total of 56 days after BDL, myocardial fibrosis was seen (Pd56 < 0.001) accompanied by macrophage infiltration (CD68: Pgroup < 0.001) and systemic inflammation (TNFα: Pgroup < 0.001, white blood cell count: Pgroup < 0.001)." (PMID 37175858, 2023). "Our results are consistent with previous findings that inflammatory cytokines such as TNF‐α and chemokines such as MCP‐1 contribute to the pathogenesis of myocardial fibrosis and consequent impairment of diastolic function induced by pressure overload." (PMID 35005845, 2022). "Proinflammatory cytokines such as tumor necrosis factor (TNF-α), interleukin 1β (IL-1β), and interleukin 6 (IL-6) can inhibit myocardial contraction, promote myocardial fibrosis, and increase collagen synthesis in pathological cardiac hypertrophy." (PMID 36270989, 2022). "Pro-inflammatory cytokines TNF-α and IL-1, and CRP, can trigger the synthesis of MMPs, leading to an increase in other markers of myocardial fibrosis, and together these can activate myocardial fibroblasts." (PMID 34088886, 2021). "Even though TNF-α and TGF-β have been assumed to influence the development of myocardial fibrosis in DCM, the exact mechanism remains elusive." (PMID 34830141, 2021). "The role of TNF-α is pleiotropic; it inhibits the functions of LOX in diabetes, osteoporosis and rheumatic arthritis, but also upregulates LOX in myocardial fibrosis and in esophagitis patients." (PMID 32708046, 2020).
Myocardial fibrosis (continued). "The myocardial fibrosis can be myocyte death, inflammation, enhanced workload, or hypertrophy and is often aggravated by the renin-angiotensin system (RAS), cytokines (TNF-α), growth factors (such as TGF-β1 and CTGF), and matricellular proteins." (PMID 32982761, 2020). "In TNF-α-dependent myocardial fibrosis, however, LOX upregulation was noted and found to be due to TNF-α activation of TGF and PI3K signaling." (PMID 32708046, 2020). "Upregulation of NF-κB expression leads to increased production of proinflammatory cytokines, such as tumor necrosis factor-α (TNF-α), interleukin-1β (IL-1β), and IL-6, which contribute to cardiomyocyte apoptosis and myocardial fibrosis." (PMID 29682154, 2018). "In cardiovascular diseases, senescence is a well-recognized process that contributes to inflammation and myocardial fibrosis and stimulates the production of several factors including IL-6, IL-8, TGF-β, and tumor necrosis factor α (TNFα)." (PMID 29181122, 2017). "It is postulated that after MI, activation of NF-κB resulted in the expression of proinflammatory cytokines such as TNF-α and MCP-1 in cardiomyocytes, which promoted the infiltration of inflammatory cells, contributing to myocardial fibrosis." (PMID 24171042, 2013). "QSYQ down-regulated the TNF-α-NF-κB and IL-6-STAT3 signaling pathways that QSYQ inhibited type I and type II collagen synthesis, thereby improving myocardial remodeling and inhibiting myocardial fibrosis." (PMID 40881586, 2025). "Finally, in vivo studies in DCM mice demonstrated that ZL significantly mitigated myocardial fibrosis and down-regulated the expression of p-P38MAPK, TNF-α, α-SMA, and Collagen-I proteins in myocardial tissue." (PMID 40373162, 2025). "The research demonstrated that the colchicine delivery system encapsulated in nanoparticles effectively reduced the levels of serum C-reactive protein (CRP), tumor necrosis Factor-alpha (TNF-α), and IL-1β, decreased the infarct area by 45%, and alleviated myocardial fibrosis." (PMID 41299461, 2025). "Studies on TNF‐α knockout mice revealed that inhibition of TNF‐α production attenuated the inflammatory response after myocardial injury, leading to a reduction in reparative myocardial fibrosis and improvement in cardiac function." (PMID 39087342, 2024). "Particularly, resveratrol results in improving adriamycin-induced myocardial fibrosis by increasing SIRT1 and by decreasing factor β1 (TGFβ1), which lead to an increase of glutathione (GSH) and SOD and a decrease of MDA, Hyp, TNF-α and creatine kinase-MB (CK-MB)." (PMID 36615832, 2022). "The results showed that B-cell deletion reduced the expression of the cytokines TNF-α, IL-1β, IL-6, and TGF-1β, decreased myocardial collagen synthesis after AMI, alleviated myocardial fibrosis, improved left ventricular remodelling, and maintained the left ventricular ejection fraction." (PMID 33407160, 2021). "Activated B cells promote cytokine (TNF-α, IL-1β, IL-6, TGF-1β) secretion and may participate in the pathological process of myocardial injury after AMI, which is related to myocardial fibrosis after AMI." (PMID 33407160, 2021). "Furthermore, it was shown that TNF-α-secreting B cells were increased in blood samples of DCM patients and that TNF-α can contribute to myocardial fibrosis in DCM." (PMID 34830141, 2021). "It suppresses TNF-α and IL-1β synthesis by activating one of its target genes, the Suppressor of Cytokine Signaling (SOCS)-3, thus preventing from collagen synthesis by activated myofibroblasts and from myocardial fibrosis." (PMID 32117843, 2020). "The expression of inflammatory factors such as tumor necrosis factor-α (TNF-α) and interleukin-6 (IL-6) was demonstrated to promote cardiac fibroblast proliferation, thereby increasing collagen synthesis and ultimately leading to myocardial fibrosis." (PMID 31885827, 2019). "In addition, TNF induces cardiomyocyte apoptosis, and IL6 induces hypertrophy and myocardial fibrosis." (PMID 28163696, 2017).
Myocardial fibrosis (continued). "Furthermore, the inflammatory mediators (NF-κB p65, TNF-α, MCP-1) were down-regulated by GXD in the myocardial fibrosis rats." (PMID 26846090, 2016). "GXD down-regulates the expression of NF-κB target cytokines such as TNF-α, monocyte chemotactic protein-1 (MCP-1), and inhibits the TGFβ1/Smads signaling pathway, thereby inhibiting myocardial type I and type II collagen synthesis and attenuating the cardiac injury cuase by myocardial fibrosis." (PMID 40881586, 2025). "Qishen-yiqi dropping pills may have anti-myocardial fibrosis effect through HIF-1 signaling pathway, forkhead box O subfamily protein (FoxO) signaling pathway, TNF signaling pathway, PI3K-AKT signaling pathway and other enriched pathways, and it reduces the expression of myocardial p62." (PMID 40660593, 2025). "In addition, TNF-α directly reduces collagen synthesis in cardiomyocytes, enhances matrix metallopeptidase 2 (MMP-2) and matrix metallopeptidase 9 (MMP-9) activities, promotes collagen breakdown, and exacerbates myocardial fibrosis." (PMID 37057099, 2023). "Electroacupuncture at PC6 inhibited myocardial fibrosis on hypertension-induced myocardial fibrosis in spontaneously hypertensive rats (SHRs), which may be mediated by down-regulation of the enhanced Ang II-TGF-β1-CTGF/TNF-α pathway and up-regulation of the reduced MMP-9 expression." (PMID 35578250, 2022). "Also, the cardiac histopathology, myocardial oxidative stress markers (malondialdehyde (MDA), glutathione (GSH) and CAT) and norepinephrine (NE), myocardial fibrosis, the expression of caspase-3, TGF-β, TNF-α, and tyrosine hydroxylase (TH) in myocardial tissues were measured." (PMID 32106580, 2020). "In addition, TNF-α, as a proinflammatory cytokine, promotes collagen deposition in fibrotic myocardium myocardia and ECM accumulation by affecting MMP expression and activity, which can lead to myocardial fibrosis." (PMID 32982761, 2020). "Collectively, the results of present study suggest that 8 weeks of EA at PC6 inhibited myocardial fibrosis in SHRs, which might be mediated by downregulation of an enhanced Ang II -TGF-β1-CTGF/TNF-α pathway as well as upregulation of the diminished expression of MMP-9." (PMID 32982761, 2020). "Notably, EA was effective in reversing the expression patterns of TNF-α and MMP-9 in SHR (P < 0.01, P < 0.001), which might mediate the inhibitory effects of EA on myocardial hypertension and myocardial fibrosis." (PMID 32982761, 2020). "Additionally, studies have shown that the increase in immune cell infiltration and inflammatory cytokines such as tumor necrosis factor-α (TNF-α) and interleukin-6 (IL-6) in the myocardial tissue of HCM patients may contribute to the development and progression of myocardial fibrosis in HCM." (PMID 40271123, 2025). "Additionally, they found that patients with DCM also had an increase in the percentage of TNF-producing B cells, which correlated directly with indices of cardiac dysfunction and myocardial fibrosis, whereas no change in the percentage of IL-10-producing B cells compared to healthy controls." (PMID 35350762, 2022).